RN7SL652P (RNA, 7SL, cytoplasmic 652, pseudogene)
Gene: Miscellaneous RNA gene on chromosome 11 (47,557,534 to 47,557,833, reverse strand). Ensembl gene ENSG00000265559.
Homologues: Orthologues: chimpanzee Metazoa_SRP (97% identical), macaque Metazoa_SRP (91% identical). Paralogues in human: RN7SL1 (86% identical), RN7SL2 (85% identical), RN7SL3 (84% identical), RN7SL126P (81% identical), RN7SL7P (81% identical), RN7SL220P (81% identical), RN7SL803P (81% identical), RN7SL91P (81% identical), RN7SL18P (80% identical), RN7SL448P (80% identical), RN7SL45P (80% identical), RN7SL769P (80% identical), and 703 more.